NRF1 (nuclear respiratory factor 1)
Diseases named in the same sentence as NRF1 in open-access papers (continued):
Sharing a sentence is not in itself a finding about the gene and the disease.
tumor (85 papers, 2004 to 2025). "When the tumor microenvironment is in hypoxia, the hypoxia‐induced E3 ligase SIAH2 degrades NRF1, which downregulates the expression of nuclear‐encoded mitochondrial genes, leading to an enhanced pro‐tumor immune response." (PMID 39748782, 2025). "Tumor number was elevated in male mice with Nrf1 deficiency, and interestingly, this effect was lost in mice deficient for Nrf1 and Nrf2." (PMID 39125617, 2024). "In fact, our previous work had revealed that knockdown of Nrf1 caused a significant malignant growth of subcutaneous tumor xenografts in nude mice." (PMID 34268128, 2021). "Dampening NRF1 degradation under hypoxia not only impairs the polarization of TAMs, but also promotes tumor cells to become more susceptible to apoptosis in a FADD-dependent fashion, resulting in secondary necrosis due to the impairment of efferocytosis." (PMID 30833558, 2019). "NRF1/2 protein turn-over in tumor cells is controlled by the kelck-like EZH-associated protein 1 (KEAP1) and other ubiquitin ligase complexes." (PMID 29487387, 2018). "We also observed that phosphorylation-deficient NRF1 mutants (mutation at amino acid residues 109 and 203 of the NRF1 protein sequence) suppressed the susceptibility of the BTICs to develop tumor spheroids when exposed to E2." (PMID 30486409, 2018). "Altering the activity of hepatic Nrf1, Nrf2, or both had a largely similar impact on males and females, except that the magnitude of the effect was in some cases more dramatic in one sex and tumor incidence was only different in hepatic Nrf1-deficient males." (PMID 39125617, 2024). "NRF1 expression was associated with tumour size and poor prognosis in patients." (PMID 35448958, 2022). "Significantly, the axiomatic rationale underlying distinct animal xenograft tumor phenotypes has also been unraveled by transcriptomic analysis of the genome-wide gene expression in Nrf1α−/−, Nrf1α−/−+siNrf2, Nrf2−/−ΔTA and caNrf2ΔN cell lines, when compared with wild-type Nrf1/2+/+." (PMID 30562963, 2018). "NRF1 inhibitor further increased the tumor burden and decreased the survival of tumor-bearing mice treated with BBζ-Neo." (PMID 40025022, 2025). "Altogether, such debating results presage a good start for this topic to explore the potential roles for Nrf1/Nfe2l1 in the immune homeostasis along with anti-tumor immune and anti-inflammatory responses." (PMID 40703332, 2025). "A recent study has shown that the SIAH2–nuclear respiratory factor 1 (NRF1) axis reshapes the TME by modulating several processes such as tumor mitochondrial function, TAM polarization, and cell death." (PMID 39748782, 2025). "The E3 ubiquitin ligase (SIAH2)-nuclear respiratory factor 1 (NRF1) axis affects tumor mitochondrial activity, TAMs polarization, and cell death." (PMID 38655133, 2024). "Nrf1 has been found to repress tumor growth in HCC cell models and in aged mice with hepatic Nrf1 deficiency." (PMID 39125617, 2024). "It has been shown that tumor proliferation and Nrf1 are distinct and that malignant proliferation is inhibited after interfering with Nrf2 expression or knockdown." (PMID 38634043, 2024). "In combination with serial deletions of CD47 promoter, we defined the minimal DNA region required for its activation, as well as, specific DNA locations within that region, which are preferentially occupied by NRF-1 in tumor cells." (PMID 39742254, 2024). "We found NRF1 mRNA level was significantly elevated in tumor tissue compared with normal tissue, which was the same for the paired HCC tissue and adjacent normal tissue." (PMID 37875967, 2023). "Photographs and HE staining both revealed that silencing NRF1 impeded tumor cell metastasis to the lung." (PMID 37875967, 2023). "As expected, Western blot and immunohistochemistry (IHC) results showed that NRF1 protein expression was significantly higher in HCC tumor tissue than in adjacent normal tissue." (PMID 37875967, 2023).
tumor (continued). "We found that carfilzomib treatment of NRF1-depleted tumors resulted in significantly reduced tumor growth, along with a corresponding decrease in final tumor volume and tumor mass." (PMID 37739987, 2023). "In further support of this notion, we show here that NRF1 depletion significantly reduced tumor burden in an MDA-MB-231 TNBC xenograft mouse model treated with carfilzomib." (PMID 37739987, 2023). "Similar to the in vitro results, we found that the tumor volumes in shNRF1 group were significantly smaller than shNC group, and tumor weights were also lower upon NRF1 knockdown." (PMID 37875967, 2023). "Cluster 1 exhibited a poor prognosis and was characterized by decreases in the HIPPO-, MYC-, NOTCH-, NRF1-, TGF-beta-, PIK3-, and RAS-associated tumor pathways." (PMID 36175504, 2022). "NRF1 is a potential therapeutic target, displaying differential expression in prostate cancer tumor tissue versus adjacent non-tumor tissue." (PMID 36359002, 2022). "A recent study has linked SIAH2 to the cellular response to oxidative stress, remodeling of the tumor microenvironment, and tumor progression by targeting NRF1 for degradation in breast cancer." (PMID 33842469, 2021). "And also, drugs that target the CHOP/SIRT3/NRF1/2 signal pathway should achieve maximum tumor death or eradication efficacy." (PMID 34717757, 2021). "Meanwhile, the IHC results of tumor tissues also demonstrated that Klf5 and Nrf1 expression were down-regulated with metapristone treatment." (PMID 33413440, 2021). "Collectively, these facts authenticate that Nrf2 acts as a tumor promoter, whereas Nrf1 functions as a dominant tumor repressor and also confines oncogenicity of Nrf2." (PMID 32273945, 2020). "We predicted NRF1 as a transcription factor regulating CLCN5, and ChIP-seq data of various tumour cells verified the binding peak between NRF1 and CLCN5." (PMID 32660514, 2020). "The third group comprises V$NRF1 (Nuclear respiratory factor 1) family, closely connected with mitochondrial biogenesis, DNA damage signaling, and tumor metabolism." (PMID 33036380, 2020). "In contrast, NRF1 mRNA levels were equally abundant between almost all tumor and normal specimens (bottom)." (PMID 32123008, 2020). "Reconstituted wild-type NRF1 tumors also showed reduced M2-TAMs in the tumor tissues, however, only slightly necrosis was shown." (PMID 30833558, 2019). "Ablation of NRF1 degradation enhances tumor cell apoptosis in a FADD-dependent manner, which induces secondary necrosis due to insufficient clearance of the apoptotic cell caused by the lack of polarized TAMs." (PMID 30833558, 2019). "The degradation of NRF1 is responsible for the reduction of the expression of NEMGs and mitochondrial function in hypoxic tumor cells." (PMID 30833558, 2019). "The NRF1-BRAF fusion in our patient's tumor contains exon 1–10 of the NRF1 gene and retains the entire kinase domain of the BRAF gene." (PMID 31010895, 2019). "Herein, to elucidate what effects have been elicited by Nrf1α and Nrf2 on tumor repression or promotion, we further investigate distinct genotypic tumors derived from Nrf1/2+/+, Nrf1α−/−, Nrf1α−/−+siNrf2, Nrf2−/−ΔTA and caNrf2ΔN cells in xenograft mice." (PMID 30562963, 2018). "There are several key genes related to cell growth, cell transformation, cell adhesion/motility, and tumor suppression that are regulated by NRF1." (PMID 30486409, 2018). "In turn, albeit Nrf2 exerts a dominant tumor-promoting role in tumorigenesis and malignant growth, it can also directly mediate the Nrf1 gene transcription to form a feedback regulatory loop." (PMID 30562963, 2018).
tumor (continued). "To determine if mRNA expression of Prdx1 and its transcriptional regulators (Nrf1, Nrf2) is elevated in patients, we searched the Oncomine mRNA database of normal and tumor pancreatic tissue." (PMID 29190947, 2017). "While all of the tumor cells at both diagnosis and relapse shared the two SNVs in CREBBP and RGS11, five additional mutations in NRF1, MARCKS, USP11, ELK1, and MYC were detected at diagnosis." (PMID 26527318, 2016). "In our study, we identified NRF1 as a direct target of miR-504 that is involved in the regulation of the tumor radiation response." (PMID 26201446, 2015). "Given the inverse correlation between BRCA1 and ErbB2 levels in tumours, it was expected that some component of the NRF-1 > GABP > BRCA1 pathway would be sensitive to ErbB2-overexpression." (PMID 21609478, 2011). "Together, these suggest a possibility that Nrf1 could function as a tumor repressor in the hepatocytes." (PMID 40703332, 2025). "Therefore, it is inferable that the tumor-promoting effect of Nrf2 is stringently confined by Nrf1 as an indispensably braking control of Keap1 and proteasome functioning in distinct adaptive responses." (PMID 40703332, 2025). "Notably, HIF activates downstream glycolytic enzymes, while SIAH2 enhances the Warburg effect by ubiquitinating the downstream molecule nuclear respiratory factor 1 (NRF1) and facilitating metabolic reprogramming, thereby ensuring active tumor cell metabolism." (PMID 39227970, 2024). "Tumor incidence in female mice with hepatocyte deficiency for Nrf1, Nrf2, or both was not obviously different (i.e., <30%) than controls, and this was also the case for male mice with Nrf2 deficiency and those with combined deficiency." (PMID 39125617, 2024). "The dual role of the NRF1 in healthy and tumor tissue is in line with our proteomics findings and could contribute to the explanation of the differential activity pattern of the promoters." (PMID 39132157, 2024). "Taken together, these results suggest that physiologic Nrf1 protects against MASH progression to HCC by suppressing tumor initiation, and that this may involve functional interactions with Nrf2 activity." (PMID 39125617, 2024). "Their research also revealed that tumor cells experienced secondary necrosis due to inhibited macrophage polarization and were more vulnerable to apoptosis when efferocytosis was hampered by hypoxic inhibition of NRF1 degradation." (PMID 38655133, 2024). "Since epithelial-mesenchymal transition (EMT) is a critical process for the invasion and metastasis of tumor cells, we wondered whether NRF1 could affect EMT of HCC cells." (PMID 37875967, 2023). "Furthermore, NRF1 mRNA level was gradually elevated in tumor tissue as the TNM stage or pathological grade increased." (PMID 37875967, 2023). "Based on the previous results showing that Agr could promote apoptosis in CRC cells, we hypothesized that Agr would also suppress tumor growth by blocking PGC-1α/NRF1/TFAM signaling in vivo." (PMID 36591497, 2022). "NRF3 induces the gene expression of POMP for 20S proteasome assembly and CPEB3 for NRF1 translational repression, inhibiting tumor suppression responses, including cell-cycle arrest and apoptosis, with resistance to a proteasome inhibitor anticancer agent bortezomib." (PMID 34884489, 2021). "Furthermore, those authors demonstrated that the expression of HIF-1, GLUT-1, LDH, and MCT4 increased in GBM tissue samples from the inner region of the tumor, whereas the expression of MCT1, C-MYC, and NRF1 is higher in the lateral section of the tumor." (PMID 32707662, 2020).
tumor (continued). "Considering tumor progression depends on tumor maintenance in addition to cell proliferation, mitochondria are required for tumor growth and are reduced in the tumors during the process of tumor progression due to hypoxia-induced NRF1 degradation." (PMID 30833558, 2019). "Western blot analysis of the xenograft tumor tissues showed that the ratio of activated MLKL (p-MLKL Ser358) to total MLKL was decreased in reconstituted wild-type NRF1 or K230R cells comparing with control cells, indicating that the necrosis in the tissues is not due to MLKL-mediated necroptosis." (PMID 30833558, 2019). "We also showed that FADD was more abundant in reconstituted NRF1 and K230R xenograft tumor tissues, indicating that the increased FADD may be responsible for the dramatic apoptosis in K230R tissues." (PMID 30833558, 2019). "However, histological analysis of the xenograft tumor tissues revealed that a slight and a dramatic increase of necrotic areas in wild-type NRF1 and K230R reconstituted tumor tissues respectively." (PMID 30833558, 2019). "Taken all these data together, we conclude that the accumulated NRF1 can sustain the expression of FADD under hypoxia, which may enhance the susceptibility of tumor cells in response to extrinsic death stimuli, such as TRAIL, and lead to increased apoptosis." (PMID 30833558, 2019). "Our results also identified that mitochondria are spatially organized in response to tumor hypoxia through the degradation of NRF1 by the hypoxia-induced E3 ligase SIAH2, resulting in mitochondrial heterogeneity which consequentially potentiates metabolic heterogeneity." (PMID 30833558, 2019). "The results showed that NRF1 knockdown inhibited the tumor growth, whereas reconstituted wild-type NRF1 could completely reverse this growth retardation phenotype." (PMID 30833558, 2019). "We hypothesize that hypoxia-induced NRF1 heterogeneous expression may function differently during tumor progression." (PMID 30833558, 2019). "This is because deterioration of Nrf1α−/−-tumor results from hyper-active Nrf2, along with decreased PTEN and activation of downstream PI3K-AKT signaling, but the Nrf1/2+/+-tumor growth is unaffected by constitutive activation of Nrf2 when compared with caNrf2ΔN-tumor." (PMID 30562963, 2018). "This is validated by further evidence revealing that, upon the presence of Nrf1 in caNrf2ΔN-derived tumor cells, its growth is almost unaffected by constitutive activation of Nrf2, as well as antioxidant and detoxifying genes, when compared with equivalents of wild-type Nrf1/2+/+-bearing tumor." (PMID 30562963, 2018). "Then xenograft tumours were subjected to histopathological examination by routine hematoxylin-eosin staining, followed by immunohistochemical staining with antibodies against Nrf1." (PMID 27065079, 2016). "However, the size of the largest tumors was not greater in hepatocyte Nrf1 deficient liver, indicating tumorigenic effects were due to increased tumor initiation, not tumor growth." (PMID 39125617, 2024). "We then assessed whether NRF1 could drive tumor metastasis in vivo." (PMID 37875967, 2023). "Finally, we examined the effect of silencing NRF1 on tumor progression in vivo." (PMID 37875967, 2023). "However, NRF1 and its target genes, whose expression pattern and biological function in tumours, are largely unknown." (PMID 35448958, 2022). "Therefore, the subtle regulation of mechanisms mediated by SREBP2 and Nrf1 could negatively regulate metabolic and cellular processes present in tumor cells." (PMID 34093831, 2021). "Herein, we determined whether two antioxidant transcription factors Nrf1 (also called Nfe2l1, as a tumor repressor) and Nrf2 (as a tumor promoter) are required for glycolysis and other glucose metabolic pathways and also involved in the redox metabolic reprogramming induced by glucose deprivation." (PMID 32774674, 2020).
tumor (continued). "Furthermore, NRF3 may partly utilize the same target genes as NRF2 as well as NRF1 to promote tumor formation, because the amino acid sequences of the DNA binding domain are similar among NRF1, NRF2, and NRF3." (PMID 32123008, 2020). "Even though increased NRF1 may impact the polarization of TAMs, deficiency in TAMs polarization seems not enough to explain the dramatic necrosis in K230R tumor tissues." (PMID 30833558, 2019). "We thus examined whether altered NRF1 would affect TAMs in tumor tissues." (PMID 30833558, 2019). "These could help to identify new markers beside mTOR activity characterisation—such as FASN, CPT1a, ACSS2—or find good mitochondrial function markers (e.g. TOM20, NRF1), and to assign the metabolic expression profile of tumours before starting treatments in patients." (PMID 30574020, 2018). "Mechanistically, we showed that Drp1 overexpression activated the PGC1-α-Nrf1/2 signaling and promoted the process of epithelial–mesenchymal transition (EMT) in ESCC cells, thereby facilitating tumor cell metastasis." (PMID 40528181, 2025). "Similar to the in vitro experiments, the expression of Nrf1/2, HO‐1, SLC7A11 and TFR in HepG2 xenograft tumours was significantly increased after SSPH I treatment." (PMID 40394754, 2025). "The inhibition of NRF1 leads to a significant decrease in ATP production in CAR-NK cells and survival of tumor-bearing mice treated with BBζ-Neo." (PMID 40025022, 2025). "Then, we analyzed the expression of NRF1 and SPIDR in different tumor grades based on the TCGA-LIHC dataset." (PMID 38438958, 2024). "In our present study, we characterized a novel role of NRF-1 in melanomagenesis as a regulator of the major innate immunity checkpoint, CD47, in tumor cells." (PMID 39742254, 2024). "The master regulator of mitochondrial biogenesis, PPARG, as well as PPARGC1A and the downstream effectors and transcription factors NRF1 and BACH1, are upregulated in various metastases as compared to the primary tumor or to the target site." (PMID 38039408, 2023). "From our data, NRF1 expression presented a correlation with vascular invasion (P = 0.015), TNM stage (P = 0.004) and tumour size (P = 0.004)." (PMID 35448958, 2022). "In an SDC case an NRF1-BRAF fusion transcript was detected, which has been described before in other tumor types and is believed to lead to activation of downstream MAPK signaling." (PMID 36077692, 2022). "Multiplex immunofluorescence was performed to examine the co-localization of NQO1, NRF1 and NRF2 within the tumor and TME of 162 chemotherapy-naïve, early-stage NSCLC patients treated by primary surgical resection." (PMID 36359002, 2022). "Here, we demonstrate that NRF1 is a novel SMAD4-binding partner and that the interaction between SMAD4 and NRF1 can repress TGF-β/SMAD4–induced tumor-suppressor functions." (PMID 34070531, 2021). "On the whole, our data suggest that NRF1 is a negative regulator of SMAD4 and can interfere with TGF-β/SMAD-induced tumor suppression." (PMID 34070531, 2021). "To validate the signal transmission in MSS CRC tissues, we analyzed the correlations between IL-17A, NRF1, miR-15b-5p, and PD-L1 expression in MSS CRC tumor specimens obtained from 160 patients." (PMID 33462141, 2021). "Our study also showed that NRF1 and/or E2 increased the proportion of SOX2 and OCT4 overexpressing tumor spheroids." (PMID 30486409, 2018).